IGKV2-18 (immunoglobulin kappa variable 2-18 (pseudogene))
Synonyms: A29; IGKV218
Gene: Immunoglobulin variable (V) pseudogene on chromosome 2 (89,128,724 to 89,129,483, reverse strand). Ensembl gene ENSG00000254157.
Diseases named in the same sentence as IGKV2-18 in open-access papers:
IGKV2-18 is named in the same sentence as 2 diseases in open-access papers, as found by Europe PMC text mining. Sharing a sentence is not in itself a finding about the gene and the disease.
IGKV2-18 shares sentences with these, for which no sentence is quoted: infection (1 paper); smallpox (1).